CTLA4 (cytotoxic T-lymphocyte associated protein 4)
Diseases named in the same sentence as CTLA4 in open-access papers (continued):
Sharing a sentence is not in itself a finding about the gene and the disease.
tumor (continued). "Increased immune checkpoint gene suppressed the anti-tumor immune response of T cells by increasing the expression of PD-1 and CTLA4 reporters." (PMID 35309900, 2022). "This is consistent with the previous study result that Tregs can inhibit the activation of CD8+ T cells through CTLA4, triggering tumor immunosuppression." (PMID 35812372, 2022). "The anti-tumor response of a T cell exhibits a state of exhaustion, such as high expression of PD-1 and CTLA-4, in cancers." (PMID 36231064, 2022). "Another study extended the concept by showing the role played by TNF in promoting activation-induced cell death (AICD) of CD8+ tumor-infiltrating lymphocytes (TILs) upon anti-PD-1 and anti-CTLA-4 combination therapy in mice." (PMID 36016934, 2022). "A small but significant decrease in tumor growth, comparable to CTLA-4 blockade alone, was observed." (PMID 35379805, 2022). "FOXP3 increases the expression of CD25 and CTLA4 and reduces tumor immunity by suppressing the production of effector cytokines such as IL-2, IFNγ, IL-4, and IL-17." (PMID 36132149, 2022). "By inhibiting PD-(L)-1 and CTLA-4, ICIs can facilitate immune surveillance and enhance immune attack in the tumor immune microenvironment." (PMID 36703957, 2022). "Targeting CTLA-4 to treat tumours requires blocking the interaction between CTLA-4 and its CD80/CD86 ligand." (PMID 36195696, 2022). "In the same study, while TIGIT+ T-cells were mostly PD1+ or CTLA-4+ in all tumor-bearing models, TIGIT+ NK cells were mostly both PD1– and CTLA-4–." (PMID 35008385, 2022). "Combination treatment with the TLR1/2 ligand Pam3CSK4 and anti-CTLA4 mAb improved the anti-tumor immunity compared with anti-CTLA4 mAb alone." (PMID 35309296, 2022). "Markers of innate immune cells (Natural Killer cells, Dendritic Cells and macrophages) are predominant in CD45+ cells immediately adjacent to PDAC tumor, however, the checkpoint protein CTLA4 is also overwhelmingly expressed, fostering tolerance." (PMID 35836806, 2022). "Increased DLL1 levels in the TME sensitized anti-cytotoxic T lymphocyte-associated protein 4 (anti-CTLA4) treatment in its resistant tumors, leading to tumor regression and longer survival." (PMID 36008793, 2022). "For the tumor cells, there were 6 (26%, PD-L1), 0 (0%, PD-1), 3 (13%, CTLA-4), and 3 (13%, IDO) cases showing IHCs positivity." (PMID 36104728, 2022). "Pai and colleagues proposed an anti-CTLA4 blocking technique that simultaneously reduces tumor invasion, maintains the anti-tumor effect, and minimizes toxicity." (PMID 36035140, 2022). "Immune checkpoint blockers, such as CTLA-4 and PD-1/PD-L1 inhibitors, promote the development of tumor immunological responses for LGG, strengthening the unique role of tumor immune system responses." (PMID 36408463, 2022). "We found that the efficacy of anti CTLA-4 linearly decreased as the tumor progressed whereas the efficacy of anti PD-1 peaked in d9." (PMID 36685577, 2022). "Other checkpoint inhibitors, such as PD-L1 and CTLA-4 can be potential targets to stimulate anti-tumor immune response." (PMID 36613878, 2022). "PD-L1 blockade and CTLA-4 inhibitor ipilumumab were reported to attenuate tumor induced inhibitory signal transduction, stimulate T cell activation, and play an anti-tumor role." (PMID 36313645, 2022). "The anti-PD-1/PD-L1 antibody plus anti-CTLA-4 antibody combination is expected to have a synergistic effect due to these different mode of actions between the two antibodies toward the tumor immune microenvironment." (PMID 35205802, 2022). "In conclusion, these findings demonstrate that there is a wide range of ICs expressed in OAC patients that represent potential therapeutic targets, outside of the well-known PD-1 and CTLA-4 axis, to propagate immune responses promoting tumour eradication." (PMID 35366537, 2022).
tumor (continued). "In doing so, the prevention of CTLA-4 or PD-1 from binding to their respective ligands unleashes effector T cells’ responses at the tumor level, reversing their exhaustion, reactivating adaptive and innate functionality and increasing tumor cells elimination." (PMID 35327411, 2022). "We previously devised a CTLA4-PD-L1 DNA cancer vaccine (DNA vaccine) and demonstrated its therapeutic effects on reducing tumor growth in a thioacetamide (TAA)-induced rat intrahepatic CCA (iCCA) model." (PMID 36341387, 2022). "Superior tumor regression was obtained by combining VEE-TRP-2 administration with antagonist anti-CTL antigen-4 (CTLA-4) or agonist anti-glucocorticoid-induced tumor necrosis factor receptor (GITR) monoclonal antibodies (mAbs)." (PMID 36140364, 2022). "Anti-CTLA-4 therapy dramatically increases tumor-specific T cell responses in patients with metastatic castration-resistant PCa (mCRPC), which is also an immunological “cold” tumor." (PMID 35401745, 2022). "The structural differences between PD-L1 and PD-1, CTLA-4, we observed that the expression of the same tumor was significantly different." (PMID 36147250, 2022). "Infiltration of myeloid-derived suppressor cells (MDSCs), tumor-associated macrophages (TAMs), Tregs, and expression of PD-1, PDL-1, and CTLA-4 can alter the TME condition in favor of tumor growth and development." (PMID 36300095, 2022). "It is therefore possible that, in PDAC, a high level of CD163+ TAMs exert immunosuppressive activity by inducing CTLA4 expression in tumor-infiltrated T cells." (PMID 35418199, 2022). "Current studies suggest that the upregulated expression of PD-L1 and CTLA4 on the surface of tumor cells plays a key role in the ability of tumor cells to escape from the host immune system." (PMID 36052090, 2022). "On the other hand, CTLA-4 blockade can enhance tumor-specific T cell priming mediated by antigen-presenting cells (APCs) expressing B7 ligands." (PMID 35237846, 2022). "Patients in the low KPNA2 group were markedly associated with higher levels of the cytotoxic T-lymphocyte-associated protein 4 (CTLA-4), program death-1 (PD-1), cytotoxic activity (CYT), tumor-infiltrating lymphocytes (TILs)." (PMID 35860570, 2022). "They demonstrated that anti-CTLA-4 monoclonal antibody IPI combined with radiotherapy made the tumor substantially subsided in both clinical trials and mouse models of metastatic melanoma, although drug resistance can be a potential concern." (PMID 35371055, 2022). "Malignancies in the hot tumour group have generally shown a better outcome in response to ICIs, such as anti-PD-1, anti-PD-L1, and anti-CTLA-4 drugs; thus, an alternative therapeutic strategy for cold tumours needs to be explored further." (PMID 36552993, 2022). "Combination of tumor-targeted RT with anti-CTLA-4 can induce effective immune responses to poorly immunogenic tumors 4T1 mouse TNBC." (PMID 34875483, 2022). "The polymeric macroparticles successfully co-released IL-2 and anti-CTLA-4 inducing dual effects in activating and promoting tumor antigen-specific T cells." (PMID 35273607, 2022). "A higher tumor TIDE score is associated not only with worse ICB response but also with worse patient survival under anti-PD1 and anti-CTLA4 therapies." (PMID 35795206, 2022). "CTLA-4 is a ligand or receptor for tumor cell-immune cell interactions and acts as an immunomodulator." (PMID 36291069, 2022). "Results showed a significant reduction in the heterotopic tumor volume with anti-CTLA4 or anti-PD1 treatment compared to the control Ig group." (PMID 35874730, 2022). "Further understanding of the impact of chemo(radio)therapy on the tumor microenvironment, particularly the CTLA-4 and CD86 signatures, is required to optimize the design of clinical trials." (PMID 36428666, 2022). "Usually, it is considered that an increased tumor TIDE score is associated with a worse ICB response, as well as a lower likelihood of survival under anti-PD1 and anti-CTLA4 therapy." (PMID 36199577, 2022).
tumor (continued). "Co-inhibitory receptors, including programmed cell death 1 (PD-1) and cytotoxic T lymphocyte antigen 4 (CTLA-4), function as pivotal checkpoints in constraining immune reactions targeting the tumor." (PMID 36335094, 2022). "Upon treatment with anti-CTLA-4 and anti-PD-L1, “concomitant immunity” was partially recovered in large-sized tumor-bearing mice." (PMID 35922755, 2022). "In a curative setting, pre-surgery, neoadjuvant anti-PD-1 monotherapy alone or combined with cytotoxic T-lymphocyte-associated protein 4 (CTLA-4) ICB induces a major response, with >90% pathological tumor regression in 20–35% of HNSCC patients." (PMID 36551718, 2022). "It is not only overexpressed in a wide variety of tumors but also has been shown to be expressed on myeloid cells associated with tumor infiltration, where it serves to dampen tumour immune responses and reduce the efficacy of anti-CTLA4 therapy." (PMID 36581692, 2022). "In contrast to this observation, it has been reported that mice that received anti-TNF added to combined CTLA-4 and PD-1-blockade had a higher rate of tumor control and survival than mice that were treated with CTLA-4- and PD-1-blockade only." (PMID 35538491, 2022). "In contrast, a marked difference was observed on Treg populations between the two tumor types when the mice were treated with anti-CTLA-4." (PMID 35523809, 2022). "Agonists targeting STING in combination with CTLA-4 or PD-1 inhibitor also exerted refreshing efficacy in the CRC model with complete tumor regression and long-lasting immune memory." (PMID 36003387, 2022). "In this study, we found that some CD8 T cells expressed high levels of immune checkpoint genes in tumor or metastatic lymph node, such as PD-1, PD-L1 and CTLA4, suggesting that ICIs can be effective for CC treatment." (PMID 35812401, 2022). "Unexpectedly, a high level of SPINK1 expression was found to be significantly and positively correlated with the high expressions of PD-1, LAG-3, TIM-3, TIGIT, and CTLA-4 in the tumor samples from the TCGA cohort." (PMID 35924241, 2022). "Although using Pulsed radiation with anti-CTLA-4 was efficient to control both treatment sites, in our observations the tumor response in the primary tumor was more evident than the secondary tumor." (PMID 36275767, 2022). "Antibody-mediated blockade of PD-1/PD-L1 and/or CTLA-4 immune checkpoint molecules reverses T cell dysfunction and restores effective anti-tumour immune responses." (PMID 35017553, 2022). "Anti–mouse CTLA-4 mAb (9D9) in combination with LEM significantly inhibited 4T1 tumor growth more effectively than either monotherapy alone." (PMID 35239514, 2022). "So the CTLA4 checkpoint inhibitor can enhance immune responses against tumor cells that can express neoantigen, leading to tumor cells being killed." (PMID 35517794, 2022). "Immune checkpoint blocking therapy for CTLA4 or PD-1 (PD-L1) has made great breakthroughs in the treatment of different types of tumours." (PMID 36700205, 2022). "Increased neoantigen production from radiotherapy can broaden the repertoire of anti-tumor T-cells to which anti-CTLA-4 can act in tandem to promote T-cell activation and expansion." (PMID 35326731, 2022). "ICIs, including PD-1, PD-L1, and CTLA-4 antibodies, can enhance the activity of effective T cells and suppress immunosuppression in the tumor microenvironment." (PMID 36276981, 2022). "Unexpectedly, abundant of cytotoxic cells were observed in the adjacent tissues, while the T-cells exhaustion markers LAYN and CTLA4 were overexpressed in the tumor tissues." (PMID 35256589, 2022). "Neoantigens in turn are able to elicit tumour-specific immune responses which can then be amplified by the immune-activating actions of immunotherapy including inhibitors of CTLA-4, PD-1 and PD-L1." (PMID 35324914, 2022).
tumor (continued). "In addition, CTLA-4 (cytotoxic T lymphocyte antigen-4, CD152), as a coinhibitory receptor on the surface of T cells, is another typical T-cell-associated immune checkpoint inhibitor signaling pathway that mostly mediates tumor immunosuppression through antigen-specific signaling pathways." (PMID 35892835, 2022). "Exosome-relevant phenotype B had a poorer prognosis and an inflamed tumor microenvironment (TME) relative to phenotype A. Patients with phenotype B presented higher responses to the anti-CTLA4 inhibitor." (PMID 35721114, 2022). "Specifically, B7 and PD-ligand 1 (PD-L1) on the tumor surface bind to CTLA-4 and PD-1, respectively, thereby preventing the T cells from attacking the tumors." (PMID 35565217, 2022). "Other studies also have documented the importance of IFNγ in the CTLA-4 blockade-mediated anti-tumor response." (PMID 35392976, 2022). "Once infiltrated into the tumor microenvironment, active Tregs overexpress inhibitory molecules CTLA-4, PD-1, TIM-3, LAG-3, and TIGIT, which together inhibit the antitumoral immune response." (PMID 36016924, 2022). "The ICI regimen was carried out with the intraperitoneal injection of anti-PD-1 and anti-CTLA-4 (three doses, three days apart, starting three days after tumor implantation)." (PMID 35890355, 2022). "Several studies have shown that tumor cells can escape immune surveillance by engaging inhibitory molecules on T cells such as CTLA-4, programmed death-1 (PD-1), and CD39." (PMID 36358898, 2022). "At present, the immunotherapy targeting PD-1, PD-L1, and CTLA4 has shown remarkable efficacy on tumor immune activation." (PMID 35711939, 2022). "In particular, the advent of direct tumour targeting mAb like rituximab and trastuzumab, and immunomodulatory mAb which block immune checkpoints such as PD-1, PD-L1 or CTLA-4, have demonstrated impressive clinical efficacy." (PMID 35288635, 2022). "Radiation can stimulate the upregulation of immune checkpoint inhibitory molecules, such as programmed cell death ligand 1 (PD-L1) on tumor cells and PD-1 or CTLA-4 on cytotoxic T cells (CTLs)." (PMID 36713375, 2022). "Treg cells can enhance tumor progression and repress antitumor immune responses, and the usage of anti-CTLA-4 antibodies can effectively kill effector Treg cells." (PMID 36134033, 2022). "Combined treatment with CTLA-4 (ipilimumab) and PD-1 (nivolumab) inhibition or BRAF/MEKi, if the tumor shows the specific mutation, are among the only useful options for patients who recur on adjuvant therapy." (PMID 36142629, 2022). "CTLA-4 was significantly increased on the surface of tumour-infiltrating CD4+ T cells compared with those in circulation in the treatment-naïve setting (p = 0.03)." (PMID 35366537, 2022). "These immuno-scores, including TMB (tumor mutational burden), PD-L1, CTLA4, or immune-related genes (HLA-B, HLA-A, HLA-DRA), expand knowledge in tumor immune status and provide a potent prediction tool for the future." (PMID 36451642, 2022). "We found that higher levels of tumour-infiltrating T cell subsets, including CD8+PD-1+LAG-3+TIM-3+, CD4+FoxP3+CTLA-4+ T and CD68+STING+ cells, were associated with inferior overall survival (OS) in 80 patients." (PMID 35982052, 2022). "The downregulation of LDHA limits the function of Tregs and contributes to a sustainable anti-tumor response during anti-CTLA-4 treatment." (PMID 36620597, 2022). "Activation of the immune checkpoint receptors cytotoxic lymphocyte-associated antigen 4 (CTLA-4) and programmed cell death protein 1 (PD1) on T-cells can crucially promote tumor immune evasion." (PMID 35198053, 2022). "Immune checkpoint inhibitors (either anti-CTLA-4 or anti-PD-1/PD-L [Pembrolizumab]) work by allowing T-lymphocytes to overcome checkpoints imposed by tumor cells, thus galvanizing the anti-tumor immune response." (PMID 35045806, 2022).
tumor (continued). "The immune landscape relates to the balance between immune-activating and immune-suppressing mechanisms, ultimately controlling tumor-escape, as recently investigated in cancers undergoing anti-CTLA4 and anti PD-1 antibodies treatment." (PMID 36224560, 2022). "Among immune check points, one that is important in tumor cells is inhibitory immune check points, namely CTLA-4 and PD-1." (PMID 36293435, 2022). "Drugs targeting immune checkpoints, such as CTLA-4, PD-1, and PD-L1 can enhance anti-tumor immune responses and allow T cells to more effectively eradicate cancer cells." (PMID 35428347, 2022). "CTLA4 is a crucial inhibitor of T cell proliferation and promotes the immunosuppressive tumor microenvironment in HCC." (PMID 36245978, 2022). "HIF-1α decreases the susceptibility of cancer cells to T-cell-mediated cytotoxicity, contributing to tumor immune escape by increasing CTLA-4 expression on CD8+ T cells and PD-L1 expression on hypoxic cancer cells." (PMID 35493517, 2022). "As crucial immune checkpoint molecules, programmed death-1 (PD1), programmed death-ligand 1 (PD-L1) and cytotoxic T ymphocyte antigen-4 (CTLA-4) play important roles in tumor immune escape." (PMID 35574298, 2022). "In fact, anti-CTLA-4 antibodies reduce the number of Treg at the tumour site, inhibit their negative regulatory effects, and enhance the antitumour immune response." (PMID 36011012, 2022). "Within the isolated CD8+ TIL populations, we identified different phenotypes according to expression of the co-inhibitory receptors PD-1 and CTLA-4, the tumor-antigen specificity marker CD39 and the activation marker CD137." (PMID 35740561, 2022). "Co-inhibitory receptors Cytotoxic T-lymphocyte antigen 4 (CTLA4), programmed cell death protein 1 (PD-1), and programmed cell death ligand 1 (PD-L1) is expressed in the tumor microenvironment." (PMID 36091162, 2022). "Next, we evaluated the activities of tumor growth inhibition following treatment with different ICIs, such as anti-PD-1/anti-PD-L1/anti-CTLA-4 antibodies, combined with regorafenib/cabozantinib plus chidamide-k30 regimens in CT26 tumor-bearing mice." (PMID 36142591, 2022). "Among the ICIs, PD-1/PD-L1 and CTLA-4 inhibitors have exhibited encouraging therapeutic outcomes, and some have been indicated for various tumor treatments since 2011, whereas others are under clinical trials." (PMID 35392976, 2022). "The prominence of IFNγ was confirmed through the aptitude of neutralizing antibodies to abolish the anti-tumor impacts of anti-CTLA-4 wholly." (PMID 35392976, 2022). "Programmed death-1 (PD-1) and cytotoxic T lymphocyte antigen-4 (CTLA-4) interact with their ligands found on the surface of antigen presenting cells (APC) or tumor cells (PD-L1/2 and CD80/86)." (PMID 35707528, 2022). "This strongly suggests that commensal flora play a key role in host-tumour immunity and are required for response to CTLA-4 inhibition." (PMID 35876944, 2022). "It was revealed that when CTLA-4 antibodies block the activity of CTLA-4 in pre-established tumors in several murine models of tumor, the tumor is rejected." (PMID 35145371, 2022). "High expression of CTLA-4 on tumor-infiltrating Tregs relative to peripheral Tregs promotes the localization of anti-CTLA-4 in tumors." (PMID 35326731, 2022). "Overall, the immune checkpoints PD-1/PD-L1 and CTLA-4 often weaken the efficacy of immune cells when modulating tumor immunity, ultimately leading to tumor cell escape." (PMID 35159131, 2022). "First, we evaluated how early treatment with anti CTLA-4 (injection on d6 and d10) affected the anti-tumor response by comparing d14 tumors, spleen, and PB from treated mice to d10 and d14 tumors, spleen, and PB from untreated mice." (PMID 36685577, 2022). "Recent studies have reported that combining anti-PD-L1 with anti-CTLA4 increased the function of tumor-infiltrating lymphocytes and restored HCC-derived T-cell responses to tumor antigens." (PMID 35720008, 2022).